IL33 (interleukin 33)
Diseases named in the same sentence as IL33 in open-access papers (continued):
Sharing a sentence is not in itself a finding about the gene and the disease.
colitis (continued). "Thus, we also focused on the function of ILC2s as key regulators in counteracting DSS-induced colitis upon IL-33 treatment." (PMID 34335571, 2021). "Consequently, other cell types targeted by IL-33 must be responsible for the harmful course of CR-driven colitis." (PMID 33654214, 2021). "Future study of the action of IL-33-producing fibroblasts during colitis may uncover new pathways to translate for UC treatment." (PMID 33953267, 2021). "This suggests that Spry2IEKO mice, which have increased tuft and goblet cell numbers and elevated IL-33, might be protected from experimental colitis." (PMID 33547321, 2021). "To begin to understand what difference might be leading to differences in regulation of IL-33 in the two models of murine colitis, we examined tissue RNA expression for two cytokines that have previously been shown to induce IL-33, TNF and IL1-β16." (PMID 33953267, 2021). "Importantly, the concentrations of CCL-2, IL-1β, and IL-6 were significantly downregulated after DSS-induced colitis mice were treated with curcumin; IL-33 and IL-10 were significantly upregulated." (PMID 34567209, 2021). "To determine whether IL-10 is required for induction of IL-33 during colitis, we exposed Il10−/− mice to DSS." (PMID 33953267, 2021). "Several studies already proposed a potential involvement for IL-33 in the development of colitis: activated eosinophils, together with increased colonic IL-33 mRNA expression levels which correlated with increased colonic eotaxin-1 expression have been demonstrated in UC patients." (PMID 34737752, 2021). "On the other hand, deficiency of the IL-33/ST2 signalling pathway was shown to protect mice from DSS or TNBS induced colitis and exogenous IL-33 application was recognized to exacerbate bacterial induced colitis." (PMID 34335571, 2021). "could show that depletion of Tregs via anti-CD25 application significantly abrogated the impact of IL-33 on reducing the development of colitis using the TNBS-induced colitis model." (PMID 34335571, 2021). "We found that colon mucosal Il1b expression was induced to a much higher degree in DSS-induced compared to Il10−/− colitis, and that IL-1β induced Il33 from colon fibroblasts in vivo, however IL1R signaling was not required for induction of Il33 expression during DSS." (PMID 33953267, 2021). "Il33-expressing fibroblasts are not induced during spontaneous chronic colitis in Il10−/− mice and IL-33 deficiency does not affect colitis development or severity in Il10−/− mice." (PMID 33953267, 2021). "We aimed to determine whether IL-33 influences Il10−/− chronic colitis and its cellular source in health and during colitis." (PMID 33953267, 2021). "Moreover, we identified that Tregs and ILC2s are the central target cells of IL-33 in the DSS-induced colitis model to drive tissue protection." (PMID 34335571, 2021). "To understand the temporal kinetics of Sprouty2 regulation by colitis and how it relates to IL-33 levels, we subjected wild-type C57/Bl6 mice to the same model of DSS colitis as above (3% in drinking water for 4 days, followed by 3 days chase on standard water)." (PMID 33547321, 2021). "We sought to determine what molecular differences between DSS and Il10−/− colitis could lead to this difference in Il33 induction." (PMID 33953267, 2021). "Notably, IL-33 has been studied in numerous inflammatory disorders, including colitis, rheumatoid arthritis, and allergic asthma, as well as sepsis, in which IL-33/ST2 signaling contributes to organ injury and innate immunity." (PMID 33178181, 2020). "We wondered whether innate lymphoid cells (ILCs) or adaptive T and B cells were involved in the therapeutic capacity of IL-33 to protect from hypervirulent C. difficile colitis." (PMID 31221971, 2019). "A novel finding is that IL-33 ameliorates experimental colitis through enhancing autophagy in mice." (PMID 30651971, 2019).
colitis (continued). "Conversely, IL-33 is a detrimental factor in other settings, such during autoantibody-induced arthritis, eosinophilic asthma, cancer, early-stage colitis, and lung fibrosis." (PMID 30774633, 2019). "The third, the expression of IL-33 was downregulated in RAI16−/− colon tissues, suggesting the IL-33 related pathway might be involved in colitis process." (PMID 31862898, 2019). "This suggests that IL-33 may indirectly alter the microbiota to protect against colitis through promotion of IgA production, which is already known to be a protective factor in IBD." (PMID 31139196, 2019). "Previously, we and others have demonstrated that IL-33 ameliorates experimental colitis through promoting Th2/Foxp3 + regulatory T Cell responses in the experimental colitis in mice, and IL-33 expression actually increased in the inflamed mucosa of IBD patients, in particular in UC patients." (PMID 30651971, 2019). "Moreover, administration of IL-33 during the recovery phase of DSS-induced colitis in mice was shown to enhance recovery, by skewing the accumulation of TH2 and TREG cells over TH1/TH17 responses in the gut." (PMID 30949175, 2019). "IL-33 treatment enhances autophagy in mice with experimental colitis." (PMID 31640262, 2019). "Increased mucosal IL-33 in human UC and murine colitis may be a homeostatic response to limit inflammation, potentially through effects on epithelial barrier function." (PMID 30651971, 2019). "Furthermore, IL-33 has been found to ameliorate TNBS colitis, in a manner that was Foxp3 dependent, through promoting a Th2 and Treg response." (PMID 31139196, 2019). "Given that IL-33 is upregulated in response to both toxin expressing C. difficile and in response to a non-toxigenic human spore prep of Firmicutes, it is possible that toxin-independent factors contribute to IL-33 expression during C. difficile colitis." (PMID 31221971, 2019). "Similarly, mice with genetic deletion of IL-33 or its receptor had decreased numbers of goblet cells and more severe colitis in a model of oxazolone-induced intestinal inflammation." (PMID 29922293, 2018). "To formally assess the role of MC-dependent IL-33/ST2 signals in intestinal homeostasis, we explored if absence of the IL-33-mediated signaling pathway promoted colitis recovery in MC-deficient KIT Wsh or WT mouse models." (PMID 30518915, 2018). "The administration of IL-33 accelerated spontaneous colitis in IL-10-deficient mice but did not induce intestinal inflammation in wild-type mice." (PMID 29922293, 2018). "In addition, we found the level of Breg responses promoted by IL-33 was higher in the chronic phase of colitis than the acute phase." (PMID 30539029, 2018). "We next hypothesised that IL-33 directly modulates goblet cells and macrophages to exert its protective effects against colitis." (PMID 28404987, 2017). "However, our previous study found a significant beneficial effect of IL-33 on Th1/Th17-mediated experimental colitis, and a deleterious consequence with anti-IL-33 antibody although without reaching significance." (PMID 28423665, 2017). "Our data here suggest that AAM could be essential for inflammation recedes and tissue repair in TNBS-induced colitis by IL-33 administration, and this process is tightly controlled by Th2-type cytokines." (PMID 28423665, 2017). "We hypothesise that increased IL-33 levels during colitis might result from a compensatory mechanism against tissue damage by active inflammation itself." (PMID 28404987, 2017). "Disparate results also exist regarding the role of IL-33 in the DSS-induced colitis model." (PMID 28710436, 2017). "Adoptive transfer with IL-33-induced AAM significantly increased the number of AAM in intestinal tissues, and the AAM exerted a protective role in body weight loss during the development of colitis." (PMID 28423665, 2017).
colitis (continued). "ST2/IL-33 signaling in Tregs was first suggested to enhance their protective ability in an experimental colitis model in which IL-33 treatment ameliorated colonic tissue injury and colitis symptoms." (PMID 28484466, 2017). "IL-33 is also found to be increased in the colon tissue of animal colitis models." (PMID 28420941, 2017). "Finally, IL-33 is known tohave extenuating effects in chronic DSS-induced colitis by shifting the immuneresponse towards a Th2-like reaction." (PMID 26848037, 2016). "Murine models with DSS (dextran sulphate sodium) -induced colitis support the hypothesis of IL-33 as a dual function cytokine." (PMID 27748438, 2016). "Likewise, geneexpression of the protective cytokines IL-19 and IL-33 in the colon ofgp130757F/F LysMcre/STAT3flox mice during acuteDSS-induced colitis was similar to the gene expression levels in WT mice." (PMID 26848037, 2016). "In addition, ST2 deficiency led to decreased disease severity in TNBS- and DSS-induced mouse models of colitis whereas exogenous IL-33 exacerbated DSS-colitis." (PMID 25937893, 2014). "In the current study, we replicated previous results that showed up-regulation of IL-33 in DSS-induced colitis and, more importantly, demonstrated that resistance of IL-25−/− mice to DSS-induced colitis was associated with diminished IL-33 expression in the colon." (PMID 25937893, 2014). "In addition, three different groups demonstrated dichotomous functions of IL-33 in the setting of acute dextran sodium sulphate (DSS)-induced colitis." (PMID 23634226, 2013). "Furthermore, in a murine model of T-cell independent dextran sodium sulphate (DSS)-induced colitis IL-33-/- mice had enhanced viability, compared to wild-type controls." (PMID 21871091, 2011). "Moreover, GLP-1RA treatment modulates the expression of additional barrier-associated genes, including IL-33, mucins, and CCL20—although the direction and magnitude of regulation vary depending on the colitis model, disease timepoint, and genetic background, complicating interpretation." (PMID 40972535, 2025). "We did not observe changes in IL33 levels in the colitis of RBBP9-deficient intestines." (PMID 39631567, 2025). "Furthermore, the addition of recombinant IL33 did not cause any change in DSS-induced colitis in Rbbp9-/- mice." (PMID 39631567, 2025). "Therefore, further understanding the role of the IL-33/ST2 signaling during DSS-induced colitis might reveal new therapeutic strategies to counteract intestinal inflammation." (PMID 34335571, 2021). "Importantly, IL-33 treatment had a remarkable impact during DSS-induced colitis." (PMID 34335571, 2021). "Similarly, we demonstrate that IL-33 ameliorates TNBS-induced colitis via enhancing the autophagy." (PMID 30651971, 2019). "Thus, IL-33 signaling to ILC2s is an important mechanism of defense from C. difficile colitis." (PMID 31221971, 2019). "Likewise, the autophagy-enhanced macrophages by IL-33 could be more polarized to M2 against the TNBS-induced Th1 inflammatory injury in the setting of colitis." (PMID 30651971, 2019). "Therefore, the aim of our study was to investigate the associations between IL-33 and IBD by exploring whether IL-33 contributes to the resolution of colitis and tissue repair by functional phenotype modulation of goblet cells and macrophages." (PMID 28404987, 2017). "Furthermore, IL-33 signaling protects from murine oxazolone colitis by supporting intestinal epithelial function, and IL-33 promotes IgA production to maintain gut microbial homoeostasis and restrain IL-1α-dependent colitis." (PMID 28423665, 2017). "A recent study reveals that IL-33 stimulates ILC2 to secrete amphiregulin to promote tissue repair in experimental colitis, suggesting ILC2 at different stage of the disease and/or some subset of ILC2 (i.e., amphiregulin+ ILC2) may have protective function in the resolution of colitis as well." (PMID 29354125, 2017).
colitis (continued). "Based on ourfindings we therefore hypothesized that the altered colitis susceptibility ofgp130757F/F mice may be due to STAT3 activation in myeloidcells, and determined the expression of IL-19 and IL-33 in peritonealmacrophages of WT and gp130757F/F mice with and without LPSstimulation." (PMID 26848037, 2016). "In addition, chronic DSS colitis appears to be less severe after IL-33 administration." (PMID 23766561, 2013). "Interestingly, investigation into the role of IL-33 in the development of colitis using this model has generated mixed results, and likely reflects the dichotomous roles of IL-33 in both inducing inflammation as well as promoting epithelial restitution/repair and mucosal healing." (PMID 23062310, 2012). "Our observations indicated that muscone downregulated the expression levels of proinflammatory cytokines, including IL-1β, IL-6, TNF-α, IL-17, and IL-33, in DSS-induced colitis." (PMID 40452925, 2025). "Using an OXA-induced colitis mouse model (C57BL/6J), Waddell showed that IL-33 can protect intestinal goblet cells." (PMID 37686309, 2023). "In Peter’s experiment, the presence of IL-33 exacerbated DSS-induced colitis in mice, while genetically knocking out IL-4 abolished this effect, suggesting that IL-33 primarily worsens colitis through the Th2 immune response." (PMID 37686309, 2023). "Gene expression of IL-33 was also upregulated in human colonic tissues from IBD patients and in murine dextran sodium sulphate (DSS) model of colitis." (PMID 38566909, 2022). "IL-33, known for its close relation to inducing type 2 immunity, probably acts as a counteractor in TNBS-induced colitis." (PMID 36614065, 2022). "Recent reports suggest that cytokines known to activate ILC2s, such as IL-33 and thymic stromal lymphopoietin (TSLP), have protective effects against DSS-induced colitis." (PMID 36268010, 2022). "In a DSS-induced acute colitis model, both ST2- and IL-33-knockout mice presented a delayed intestinal inflammatory response." (PMID 36614065, 2022). "IL-33 expression is enhanced in the inflamed mucosa of IBD patients and experimental models of colitis, and has been previously shown to play both protective and detrimental roles in colitis, based on different models of colitis and analyses of cell types." (PMID 35707544, 2022). "Mice deficient in ST2 present resistance to dextran sodium sulfate (DSS)-induced colitis, whereas ST2 ablation promotes a wound-healing response following acute mechanical colonic injury, suggesting the contribution of the IL-33/ST2 axis to mucosal healing." (PMID 36614065, 2022). "Fibroblasts are the primary colonic source of IL-33 and IL-33-expressing CD90hiCD74+ fibroblasts are increased during DSS-induced colitis." (PMID 33953267, 2021). "Our data suggest that when IL-33 is expressed in the epithelium prior to the onset of disease, it conditions the epithelium against future insult (such as the chemical damage in DSS colitis)." (PMID 33547321, 2021). "During acute colitis induced with DSS, we show there is an expansion of IL-33-producing inflammatory fibroblasts similar to those reported in human UC." (PMID 33953267, 2021). "The results of this experiment showed that the expression levels of IL-33 and ST2 in colitis model animals were significantly lower than those in the Control and Control’ group, and immune proteins could alleviate intestinal inflammation by increasing the expression levels of IL-33 and ST2." (PMID 32081954, 2020). "Emerging studies have shown that the alarmin IL‐33 induces AREG production in ILC2s and Tregs in models of colitis and lung damage after infection." (PMID 32566227, 2020). "However, whether IL-33 regulates autophagy to ameliorate experimental colitis is unclear." (PMID 30651971, 2019). "The interaction of IL-33 with TREGS and TH17 cells in the gut is of particular interest given their reciprocal roles in colitis." (PMID 31231388, 2019).
colitis (continued). "In the mouse model of trinitrobenzene sulfonic acid (TNBS)-induced colitis, dextran sulfate sodium (DSS)-induced colitis or T cell adoptive transfer induced colitis, IL-33 can increase the number of Foxp3+ Tregs." (PMID 30761089, 2019). "IL-33 administration (2 μg/day, intraperitoneal injection), while facilitating Th2/Tregs responses, also enhances the autophagy in mice with TNBS-induced colitis as well as macrophages." (PMID 30651971, 2019). "However, whether IL-33 ameliorates experimental colitis through regulating autophagy is unknown." (PMID 30651971, 2019). "In conclusion, we presented strong evidences to support that IL-33 regulating autophagy plays a role, at least in part, in alleviating the inflammation in the context of TNBS-induced experimental colitis." (PMID 30651971, 2019). "To further exploring the underlying the molecular mechanisms by which IL-33 ameliorates experimental colitis, we treated mice with the vehicle ethanol, TNBS alone, TNBS combined with IL-33, and TNBS combined with PBS control, respectively." (PMID 30651971, 2019). "IL-33, a cytokine that acts on ILC2 and Th2 to promote the cytokine production, increased in IBD patients and in experimental colitis models of mice, including TNBS and DSS model." (PMID 29354125, 2017). "Supporting these findings, Schiering and colleagues described that IL-33 treatment expands Tregs, increasing Foxp3 and ST2 expression in the spleen of mice with ongoing colitis." (PMID 26082774, 2015). "Together with their ability to produce IL-33 in response to IL-25, intestinal epithelial cells are likely an important player mediating the pro-inflammatory role of IL-25 in DSS-induced colitis." (PMID 25937893, 2014). "According to the results of a new survey, IL-33 and ST2 genes are early induced in the colonic tissue during DSS-induced colitis." (PMID 25032216, 2014). "In these studies, the authors reported increased inflammatory scores in IL-33-treated balb/c mice; however, when evaluating the epithelial layer, complete reversion of the goblet cell depletion characteristic of DSS colitis was observed." (PMID 23766561, 2013). "In the DSS colitis mouse model, liraglutide-treated mice exhibited significantly lower caecal occludin mRNA levels and higher TNF-α mRNA levels compared to controls, while RegIIIβ and IL-33 mRNA levels showed an increased trend." (PMID 40426955, 2025). "Suppress colitis-stimulated tissue oxidative stress.Suppress TNF-α, IL-6, IL-1β, and IL-33." (PMID 38585461, 2024). "Il33−/− mice also suffered from increased DSS-induced colitis and did not restrict effector T cell responses, thus phenocopying eosinophil deficiency." (PMID 36509106, 2023). "Although the exact role of IL‐33 in NEC is not understood, in colitis and IBD, IL‐33 has both a pathogenic role in immune activation as well as a protective role in modulating regulatory T cells." (PMID 37697223, 2023). "A lack of ST2 in mice diminishes colitis, whereas the administration of exogenous IL-33 aggravates the condition." (PMID 36769019, 2023). "On the other hand, this potential explanation does not explain the finding of unchanged colon Il33 expression during colitis in Il10−/− mice." (PMID 33953267, 2021). "As it was shown that IL-33 induces intestinal goblet cell differentiation indirectly through IL-13 production by ILC2s, we further assessed the impact of ILC2 transfer on goblet cells during DSS-induced colitis." (PMID 34335571, 2021). "DSS exposure induced colon Il33 expression significantly compared to untreated mice, suggesting that IL-10 is not required for Il33 induction during colitis." (PMID 33953267, 2021). "Using IL-33-citrine reporter mice (Il33Cit/+), we show that vimentin+CD90+ fibroblasts are the source of IL-33 at baseline and this population increases in DSS-induced colitis." (PMID 33953267, 2021). "IL-33 is also increased in the colonic mucosa of both TNBS- and DSS-induced murine colitis." (PMID 33435303, 2021).